TIE1 (tyrosine kinase with immunoglobulin like and EGF like domains 1)
Diseases named in the same sentence as TIE1 in open-access papers (continued):
Sharing a sentence is not in itself a finding about the gene and the disease.
colorectal cancer (2 papers, 2017 to 2021). A primary or metastatic malignant neoplasm that affects the colon or rectum. "We identified colorectal cancer as a novel Tie1‐expressing tumor, with Tie1‐positive cells hardly detectable in the normal intestine." (PMID 28464467, 2017). "We report that colorectal cancer is Tie1‐positive, albeit expressing this molecule in only a small population of malignant tumor cells in vivo and not apparent under standard in vitro conditions at all." (PMID 28464467, 2017). "Tie1 expression (at the mRNA level) was also enhanced in human colorectal cancer." (PMID 28464467, 2017). "Herein, we report that Tie1 is up‐regulated in colorectal cancer." (PMID 28464467, 2017). "Tie1‐positive tumor cells highly expressed Lgr5, a stemness marker for colorectal cancer." (PMID 28464467, 2017). "Indeed, Tie1‐positive tumor cells derived from a murine model overexpressed Lgr5, a typical stemness marker for colorectal cancer." (PMID 28464467, 2017). "Moreover, in colorectal cancer, Tie-1 positive cells were enriched in tumor cells with cancer stemness properties, suggesting that Tie-1 may have potential clinical applications in targeting cancer stem cells." (PMID 34975347, 2021). "In addition, we also found a significant elevation of Tie1 in colorectal cancer (p = 4.89E‐14)." (PMID 28464467, 2017). "Using the HT29 transplantation model, we assessed the expression of Lgr5, CD44, and CD133, major human colorectal cancer stem cell markers 25, and CK20, a characteristic differentiation marker 26 by sorted Tie1‐positive cancer cells." (PMID 28464467, 2017).
endotoxemia (2 papers, 2017 to 2025). "When the interaction domain of Tie-1 with Tie-2 is cleaved off during acute endotoxemia, the ANG-2 agonist activity is blunted." (PMID 28355132, 2017).
erythroleukemia (2 papers, 2023 to 2024). Acute erythroid leukemia characterised by the presence of at least 50% erythroid precursors and at least 20% myeloblasts in the bone marrow. "TIE1 (tyrosine kinase with immunoglobulin like and EGF like domains 1) is a tyrosine kinase receptor first isolated from an erythroleukemia cell line." (PMID 36814284, 2023).
glioblastoma (2 papers, 2021 to 2023). The most malignant astrocytic tumor (WHO grade IV). "One study used IF in combination with the TFA and observed that VEGFR2, laminin 5 γ2 chain, and the mural cell marker smooth muscle actin (SMa) were expressed by glioblastoma cells that were capable of VM, and that these cells lacked the endothelial cell markers CD31, VE-cadherin, Tie1, and Tie2." (PMID 36823554, 2023).
head and neck squamous cell carcinoma (2 papers, 2023 to 2024). A squamous cell carcinoma that arises from any of the following anatomic sites: lip and oral cavity, nasal cavity, paranasal sinuses, pharynx, larynx, and salivary glands. "The data from the Gene Expression Omnibus (GEO) NPC database and the Cancer Genome Atlas (TCGA) head and neck squamous cell carcinoma (HNSCC) datasets showed that the levels of FLI1 and TIE1 are highly positively correlated." (PMID 36814284, 2023).
lymph node metastases (2 papers, 2017 to 2024). "Thus, hematogenous metastatic spread and the development of pulmonary metastases were associated with high expression of ANGPT2, F3, and TIE1, whereas lymphogenous metastatic spread and the development of lymph node metastases were associated with high expression of NRP2." (PMID 29017512, 2017).
metastatic disease (2 papers, 2019 to 2020). "Tie-1 expression was the weakest of all evaluated factors in the epithelial cells of primary and metastatic tumors (IRS 2)." (PMID 33151982, 2020). "The Tie1 levels in healthy individuals were lower than in patients with metastatic disease before chemotherapy." (PMID 31340773, 2019).
pancreatic tumors (2 papers, 2021 to 2024). "Another study reports that TNF-α, which is abundantly present in PDAC, induces EndMT and acts at least partially through TIE1 regulation in murine pancreatic tumors." (PMID 38608280, 2024). "We show that TNF-α, abundantly present in PDAC, induces EndMT, acts, at least partially, through TIE1 regulation and participates in the CAF generation process in murine pancreatic tumours." (PMID 34172716, 2021).
rheumatoid arthritis (2 papers, 2020). A chronic, systemic autoimmune disorder characterized by inflammation in the synovial membranes and articular surfaces. "In rheumatoid arthritis (RA), Tie-1, the pro-inflammation factor, is upregulated." (PMID 33193379, 2020).
schizophrenia (2 papers, 2022 to 2024). A major psychotic disorder characterized by abnormalities in the perception or expression of reality. "TCF4 was repeatedly validated as a susceptibility gene for schizophrenia, and TIE1 was implicated with vascular development and pathogenesis of vascular diseases." (PMID 34931221, 2022).
Stroke (2 papers, 2014 to 2024). Sudden impairment of blood flow to a part of the brain due to occlusion or rupture of an artery to the brain. "Six days after stroke and PTH or saline treatment, expression of regenerative factors VEGF, EPO receptor (EPOR), Ang-1, Tie-1, Flk-1, BDNF and SDF-1 in the ischemic peri-infarct region were analyzed using Western blotting." (PMID 24503654, 2014). "Compared with stroke-vehicle control mice, the levels of pro-angiogenic factors VEGF, EPOR, Tie-1 and the neurotrophin BDNF significantly increased in PTH treated mice (n = 3 in stroke and stroke plus PTH groups, respectively; P<0.05)." (PMID 24503654, 2014).
age-related macular degeneration (1 paper, 2025). Age-related loss of vision in the central portion of the retina (macula), secondary to retinal degeneration. "further demonstrated that metformin modulates the gut microbiome to increase Bifidobacterium and Akkermansia abundance, downregulate proangiogenic genes (Tie1, Pgf, and Gata2), and attenuate the development of age-related macular degeneration (AMD)." (PMID 41278472, 2025).
attention deficit-hyperactivity disorder (1 paper, 2024). A disorder characterized by a marked pattern of inattention and/or hyperactivity-impulsivity that is inconsistent with developmental level and clearly interferes with functioning in at least two settings (e.g. at home and at school). "Moreover, the sTie-1 lead cis-variant rs3768046 has been reported to be associated with the risk of attention deficit hyperactivity disorder (ADHD) via the dysregulated expression of TIE1." (PMID 38254961, 2024).
Cachexia (1 paper, 2010). Severe weight loss, wasting of muscle, loss of appetite, and general debility related to a chronic disease. "The significant positive correlation for TIE1 mRNA expression with weight loss in both the rectus abdominis and vastus lateralis muscle groups supports the idea that some chronic training-related genes are up-regulated in cachexia." (PMID 20193046, 2010). "The exercise activated genes CaMKIIβ and TIE1 related positively to weight-loss across muscle groups, indicating that this cachexia signature is not simply due to patient inactivity." (PMID 20193046, 2010).
colon cancer (1 paper, 2017). "To characterize Tie1 expression in this type of cancer in more detail, we analyzed additional human colon cancer cell lines as well as HT29 using cells from tumor‐bearing mice followed by FACS." (PMID 28464467, 2017).
congenital megacolon (1 paper, 2025). "TGex analysis (LifeMap Sciences, USA) prioritized 9 candidate variants across 7 genes (MED13, POGZ, SETBP1, SCN9A, SCO1, APTX, TIE1) associated with phenotypes including congenital megacolon, intellectual disability, motor delay, and developmental delays." (PMID 41195223, 2025).
Cushing syndrome (1 paper, 2022). Cushing's syndrome (CS) encompasses a group of hormonal disorders caused by prolonged and high exposure levels to glucocorticoids that can be of either endogenous (adrenal cortex production) or exogenous (iatrogenic) origin. "The expression of the proteins involved in angiogenesis, namely CD34, VEGF, VEGF-R2, Ang1, Ang2, Tie1 and Tie2, was assessed by immunohistochemistry in ACC (n = 22), ACA with Cushing syndrome (n = 8) and non-functioning ACA (n = 13)." (PMID 35628389, 2022).
dengue (1 paper, 2014). "We examined circulating levels of the angiopoietin tyrosine kinase receptors Tie-1 and Tie-2 and found statistically significant, albeit quantitatively modest differences in sTie-2 between dengue and leptosirosis patients, whereas sTie-1 levels were similar." (PMID 24444080, 2014).
endothelial dysfunction (1 paper, 2025). In vascular diseases, endothelial dysfunction is a systemic pathological state of the endothelium (the inner lining of blood vessels) and can be broadly defined as an imbalance between vasodilating and vasoconstricting substances produced by (or acting on) the endothelium. "TIE1 and TIE2 are receptor tyrosine kinases that govern endothelial cell survival and angiogenesis, while ANGPT2 is pivotal in mediating endothelial dysfunction and vascular permeability." (PMID 40506916, 2025).
follicular adenomas (1 paper, 2012). "In a study of 135 patients with TC, Tie-1 immunoreactivity was observed in PTC and anaplastic TC but not FTC or follicular adenomas, and it was also noted that large tumors had decreased expression." (PMID 22630170, 2012).
glioma (1 paper, 2020). A benign or malignant brain and spinal cord tumor that arises from glial cells (astrocytes, oligodendrocytes, ependymal cells). "The results showed that the proliferation, neurotrophic factors, and angiogenesis of glioma cells were directly proportional to the Tie1 expression level and number of cancer stem cells." (PMID 32174801, 2020). "qPCR and western blot results showed that Tie1 expression in HuGSCs was significantly higher thanexpression in CD44-/CD133- glioma cells." (PMID 32174801, 2020). "In conclusion, this study showed that SPIONs drive the overexpression of miR-485-5p in human glioma stem cells and efficiently inhibit Tie1 expression levels to significantly reduce the in vivo and in vitro viability of gliomas." (PMID 32174801, 2020). "This study was the first to demonstrate the function of Tie1 in gliomas." (PMID 32174801, 2020). "Therefore, this study showedthat Tie1 is an important factor that maintains glioma stem cell activity." (PMID 32174801, 2020). "Hence, we can confirm that Tie1 is an important factor that maintains glioma stem cell activity." (PMID 32174801, 2020). "SPIONs drive miR-485-5p overexpression in cells and inhibit endogenous Tie1 expression to downregulate the protein expression levels of Fgf2/GDNF/GFAP/BDNF and significantly weaken the in vivo and in vitro viability of gliomas." (PMID 32174801, 2020). "Tie1 is often studied in the occurrence of vascular development and cardiovascular diseases 10-17, At present, there are no reports on its relationship with glioma, particularly glioma stem cell viability." (PMID 32174801, 2020).
Glucose intolerance (1 paper, 2016). Glucose intolerance (GI) can be defined as dysglycemia that comprises both prediabetes and diabetes. "At 16 weeks of HFD, when robust glucose intolerance occurs together with β-cell apoptosis, both angiopoietin receptors Tie-1 and Tie-2 were upregulated (1.5- and 1.8-fold, compared to ND control), which remained higher after 24 weeks HFD." (PMID 27617438, 2016).
Hydrocephalus (1 paper, 2023). Hydrocephalus is an active distension of the ventricular system of the brain resulting from inadequate passage of CSF from its point of production within the cerebral ventricles to its point of absorption into the systemic circulation. "In conclusion, we report novel mutations in known hydrocephalus genes in 18% of our PCH probands and propose three novel candidate genes: DNAH2, TIE1 and RNPC3 in a further 11%." (PMID 36859317, 2023).
Hyperglycemia (1 paper, 2016). An increased concentration of glucose in the blood. "Similarly, we also did not observe changes in Tie-1/Tie-2 mRNA levels in the human T2D islets, as seen in mouse islets under prolonged hyperglycemia induced by high fat/ high sucrose feeding." (PMID 27617438, 2016).
ischemic stroke (1 paper, 2014). A stroke disorder caused by obstruction of blood flow to the brain, due to thrombotic (local blood clot formation) or embolic (due to a blood clot or other material traveling from another site) event. "Several trophic factors participate in the angiogenic response after ischemic stroke such as VEGF/VEGF-R, Ang-1/Ang-2, Tie-1 and Tie-2 receptors." (PMID 24503654, 2014).
liver cirrhosis (1 paper, 2021). "In this paper, we analyzed the clinical significance of serum angiogenic markers VEGF, Ang-1, Ang-2, angiopoietin receptor Tie1/2, HGF, and PECAM-1 in 62 patients with liver disease, out of which 33 were diagnosed with HCC and 29 with liver cirrhosis without signs of neoplasia." (PMID 35008171, 2021).
lymphangioma (1 paper, 2007). A benign lesion composed of dilated lymphatic channels. "We have observed Tie2 expression in LECs sorted with anti-podoplanin antibodies from HDMECs, as well as Tie1 and Tie2 in LECs from lymphangioma patients." (PMID 17584927, 2007).
Mucinous tumors (1 paper, 2020). "Mucinous tumors displayed stronger Tie-1 expression than serous tumors (p = 0.029) and clear cell lesions were associated with a lower Tie-1 expression (p = 0.001)." (PMID 33151982, 2020).
primary open-angle glaucoma (1 paper, 2023). "This is supported by emerging data implicating heterozygous TIE1 mutations in the development of childhood glaucoma." (PMID 37996923, 2023).
RASopathy (1 paper, 2023). Developmental syndromes caused by germline mutations (or in rare cases by somatic mosaicism) in genes that alter the Ras subfamily and mitogen-activated protein kinases that control signal transduction. "We describe novel variants in several LA genes, including a likely pathogenic variant in PIEZO1, and VOUS in PIEZO1, ITGA9, CELSR1, EPHB4, and TIE1, as well as novel VOUS in RASopathy genes." (PMID 36959127, 2023).
serous ovarian tumors (1 paper, 2020). "The level of Tie-1 expression was moderately, but significantly, correlated with its ligand Ang-2 IRS (r = 0.5, p < 0.001) in primary serous ovarian tumors, and the correlation was also significant with other histological types (IRS r = 0.3, p = 0.001; PP r = 0.4, p <0.001)." (PMID 33151982, 2020).
tuberculosis (1 paper, 2017). A chronic, recurrent infection caused by the bacterium Mycobacterium tuberculosis. "Concentrations of vWF and VCAM-1 were higher in mycobacteremic patients than in patients with HIV-tuberculosis without mycobacteremia, whereas concentrations of ADAMTS-13, Ang-1, and Tie-1 were lower." (PMID 28363198, 2017).
ulcers (1 paper, 2021). "Based on previous findings high expression of microvesicular receptors Tie1, 2 have been associated with the normal repair while downregulation of angiogenesis regulating factors was associated with severe ulcers which were in accordance with our findings." (PMID 33613484, 2021).
Venous malformation (1 paper, 2022). A vascular malformation resulting from a developmental error of venous tissue composed of dysmorphic channels lined by flattened endothelium and exhibiting slow turnover. "It has a high mutational component, with overexpression of genes associated with angiogenesis, such as TIE1, VEGFR2, SNF-1, TEK (kinase associated with venous malformations), and FLT1." (PMID 36555675, 2022).
tumor (52 papers, 2008 to 2025). "We studied the relationships between TIE1 and mutations, immune checkpoints (ICs), tumor mutational burden (TMB), as well as microsatellite instability (MSI) to explore the underlying mechanism of immunity in GC." (PMID 38706903, 2024). "TIE1 can be expressed in the endothelial cells of tumor blood vessels, and the loss of murine Tie1 has reduced xenograft tumor growth and angiogenesis." (PMID 37762032, 2023). "We found that high CLEC14A/PECAM1 and CLEC14A/TIE1 ratios (ratio above 95% of controls) were significantly associated with tumour pathology (odds ratio = 2.5113, 95% CI: 1.7467–3.6104 and odds ratio = 8.9821; 95% CI: 6.7440–11.9630 respectively)." (PMID 32696621, 2020). "A series of observations in our studies implied a correlation of Tie1‐positive cells with CSCs, which form a small population and associate with tumor malignancy." (PMID 28464467, 2017). "To exclude the possibility that Tie1‐positive cells originated from tumor‐associated tissues, we further investigated other typical marker proteins (CD31, CD45, and PDGFRβ for endothelial cells, white blood cells and fibroblasts, respectively)." (PMID 28464467, 2017). "Tumours grown in Tie1-deficient mice were smaller and contained less blood vessels when compared with tumours grown in wild-type mice." (PMID 27941161, 2017). "However, recent studies have shown that the loss of TIE1 enhances Notch signaling, suggesting TIE1 is a positive regulator of tumor angiogenesis." (PMID 40821121, 2025). "CD31 and Tie1 are implicated in the development of vascular integrity and tumor angiogenesis and Mtor, which encodes a component of the PI3K-AKT-mTOR pathway responsible for releasing VEGF, a crucial factor in tumor angiogenesis and is also known to transform tumor-associated macrophages." (PMID 38719996, 2024). "TIE1 deficiency in mouse tumor model decreases tumor angiogenesis and enhances vascular normalization, leading to increased tumor necrosis, which ultimately results in delayed tumor growth at later stage." (PMID 36814284, 2023). "Besides this, exploratory markers involving angiogenesis (serum VEGF, PDGF, Tie-1, and Tie2, etc.)and immune function (CD clusters, serum tumor mutation burden (TMB), etc.)are conducted via liquid biopsy." (PMID 32143730, 2020). "Interestingly, additive inhibition of tumor growth was observed when angiopoietin activity was blocked in Tie1-deficient mice." (PMID 31340773, 2019). "Next, we hypothesized that expression of Tie1 could be induced due to association with tumor stromal cells present in the tumor microenvironment." (PMID 28464467, 2017). "A closer analysis of the tumours in the Tie1-deleted mice revealed less vascular sprouts, increased EC and tumour cell apoptosis, decreased vascular perfusion and association of degenerating ECs with small intravascular fibrin deposits in the tumour vasculature." (PMID 27941161, 2017). "Tie-1 is typically expressed on vascular endothelium and has been implicated in tumor angiogenesis." (PMID 22630170, 2012). "In this study, we showed that TIE1 expression promotes primary tumor growth primarily through the suppression of apoptosis." (PMID 41235901, 2025). "In short, it has been evidenced that TIE1 is involved in tumor angiogenesis and inflammatory vascular remodeling." (PMID 40740229, 2025). "In our study, we observed a favorable association between high immune/stromal/estimate score and low tumor purity with TIE1 overexpression, indicating that immune cell infiltration was more frequent in the TIE1 high expression group." (PMID 38706903, 2024). "Consistent with the in vitro experiments, AC-73 treatment attenuated the increase in xenograft tumor volume and weight induced by TIE1 overexpression." (PMID 38617545, 2024). "More and more literature has demonstrated aberrant expression of TIE1 in diverse tumor types, with several studies indicating its potential role in promoting carcinogenesis and tumor progression." (PMID 38706903, 2024).